INS (insulin)
Diseases named in the same sentence as INS in open-access papers (continued):
Sharing a sentence is not in itself a finding about the gene and the disease.
type 2 diabetes (continued). "Previous studies that enrolled healthy persons and individuals with obesity and type 2 diabetes had reported similar findings of an inverse association between plasma levels of long-chain dihydroceramides (including C18:0, C20:0, and C22:0) and insulin sensitivity." (PMID 40630937, 2025). "The Mediterranean diet, rich in fruits, vegetables, whole grains, olive oil, and fish, has been extensively linked to improved insulin sensitivity, reduced inflammation, and better lipid profiles, contributing to lower risks of cardiovascular disease and type 2 diabetes." (PMID 41003008, 2025). "In type 2 diabetes, cellular resistance to insulin arises due to multiple underlying mechanisms." (PMID 41378205, 2025). "Although their study population differed from ours, which included only insulin-dependent individuals with type 1 or advanced type 2 diabetes, their findings support the concept that underlying adrenal dysfunction may contribute to the risk of NH." (PMID 40932945, 2025). "Our findings suggest that total cBAs and FGF-19 have potential as biomarkers of insulin sensitivity that should be considered for future studies investigating the mechanism underlying glucose metabolism alterations predicting Type 2 diabetes risk and its sequelae." (PMID 41169463, 2025). "Moreover, prolonged breastfeeding has been associated with improved glucose metabolism, increased insulin sensitivity, and reduced visceral adiposity, which are beneficial in mitigating the risk of type 2 diabetes." (PMID 40895147, 2025). "Similarly, in a 12 week intervention, men at risk of or diagnosed with type 2 diabetes showed increased peripheral insulin sensitivity following afternoon exercise, but morning exercise failed to elicit similar improvements." (PMID 40580209, 2025). "Altogether, these analyses support that SLC30A8 LoF reduces type 2 diabetes risk through a mechanism of enhanced insulin secretion and improved overall beta cell function, and that the magnitude of this effect may be proportional to the degree of SLC30A8 LoF." (PMID 41020949, 2025). "We aimed to determine whether type 2 diabetes and gestational diabetes were associated different levels of serum and cord blood adiponectin, leptin, insulin and offspring birthweight." (PMID 40045330, 2025). "Basal insulin with glucagon-like peptide-1 receptor agonist could be preferred over premixed insulin for intensification in type 2 diabetes due to better glycemic control, lower hypoglycemia risk, and favorable effects on body weight." (PMID 41268167, 2025). "Type 2 diabetes mellitus is caused by insufficient insulin production and insulin resistance." (PMID 41171710, 2025). "For instance, fermented dairy products containing live and active cultures have been associated with a reduced risk of type II diabetes, better glycemic control, reduced weight gain, and lower circulating triglyceride levels, systolic blood pressure, and insulin resistance." (PMID 41301527, 2025). "It is stated that exposure to EDs during the prenatal and postnatal period may raise the risk of type 2 diabetes in adulthood by disrupting glucose, lipid, and insulin homeostasis in the offspring." (PMID 39775248, 2025). "Similarly, in adipose tissue, SIRT4 influences lipid metabolism and insulin sensitivity, and its downregulation is linked to age-related metabolic syndrome and type 2 diabetes (T2D)." (PMID 40799515, 2025). "Indeed, elevations in AST and ALT have been associated with type 2 diabetes risk as well as declines in insulin secretion as estimated from fasting glucose and insulin (i.e. HOMA‐B)." (PMID 40018087, 2025). "Recent evidence suggests that GLP-1RAs may be associated with a reduced risk of certain cancers in individuals with type 2 diabetes in comparison to insulin therapy." (PMID 40599584, 2025).
type 2 diabetes (continued). "DASH diet significantly reduces the risk of type 2 diabetes by optimizing blood glucose homeostasis, reducing hemoglobin A1c (HbA1c), improving insulin sensitivity and insulin resistance, regulating lipid metabolism, and inhibiting oxidative stress and inflammation." (PMID 41229546, 2025). "Importantly, some individuals who are not obese on the basis of height and weight can be hyperinsulinemic, insulin-resistant and predisposed to type 2 diabetes, hypertriglyceridemia and premature coronary heart disease, like people with overt obesity." (PMID 40707205, 2025). "Moreover, a healthy diet can help regulate blood sugar and improve insulin sensitivity, which is particularly important for individuals with or at risk of developing type-2 diabetes mellitus (T2DM) or metabolic syndrome." (PMID 39940436, 2025). "Since insulin-secreting pancreatic beta cells loss is a hallmark of both type 1 diabetes (T1D) and type 2 diabetes (T2D) which are the most common forms of DM, in addition to insulin secretion, the studies aiming to compensate for beta cell loss in DM have gained an attraction recently." (PMID 40342327, 2025). "In this regard, focus on pancreatic function warrants attention for the regulation of insulin secretion since misalignment between daily rhythms of sleep, eating, or movement may raise the risk of type 2 diabetes." (PMID 40018087, 2025). "Proposed mechanisms include inflammatory cytokines, effects on insulin sensitivity, and the use of systemic glucocorticoids in severe asthma, which may increase the risk of type 2 diabetes." (PMID 40995258, 2025). "A large-scale prospective cohort study found that heme iron intake may increase the risk of type 2 diabetes through pathways such as insulin resistance, inflammation, and lipid metabolism." (PMID 40416367, 2025). "IR, defined as reduced or impaired insulin sensitivity in insulin-dependent tissues or organs manifested by impaired glucose uptake and oxidation, is an important risk factor for the development of type 2 diabetes and CHD." (PMID 40255500, 2025). "Dietary fibre can also help to control insulin levels which could have an effect on the risk of developing type 2 diabetes." (PMID 40275391, 2025). "Moreover, in the same cohort, a higher habitual MGO intake was associated with greater insulin sensitivity and less type 2 diabetes." (PMID 40722867, 2025). "However, in case of type 2 diabetes, the resistance to insulin by the liver causes overproduction of glucose by the liver when the patient is fed." (PMID 41190158, 2025). "Components of the Mediterranean diet that may benefit glucose control in individuals with type 2 diabetes include its high content in unsaturated fats and antioxidants, which are linked to improved insulin sensitivity." (PMID 40641818, 2025). "The introduction of GLP-1 receptor agonists and SGLT-2 inhibitors for managing type 2 diabetes in LMICs could significantly reduce insulin dosage and associated health risks, leading to improved outcomes and reduced disability." (PMID 40245017, 2025). "In addition gut flora-associated iron overload increases susceptibility to type 2 diabetes by reducing insulin secretion, promoting insulin resistance and facilitating hepatic gluconeogenesis." (PMID 41488463, 2025). "A prospective cohort study of 2422 normoglycemic individuals followed for 12 years found that both phenylalanine and tyrosine were linked to an increased risk of developing type 2 diabetes, potentially due to impaired insulin signaling and pancreatic β-cell dysfunction." (PMID 39796608, 2025). "Therefore, impaired insulin clearance leads to increased insulin plasma levels and is an independent risk factor for type 2 diabetes occurrence." (PMID 40365648, 2025). "Moreover, the MD is associated with improved insulin sensitivity, which plays a key role in preventing type 2 diabetes and metabolic syndrome, both conditions closely related to obesity." (PMID 40699839, 2025).
type 2 diabetes (continued). "Furthermore, plasma levels of specific ceramides and other sphingolipid species have been reported to be significantly associated with measures of insulin sensitivity and insulin secretion in studies that included individuals with obesity or type 2 diabetes." (PMID 40630937, 2025). "Oseltamivir may possess diabetogenic effects by impacting insulin signaling pathways and metabolic processes, potentially explaining its association with a higher incidence of Type 2 diabetes." (PMID 39861189, 2025). "However, sustained, high levels of gluconeogenesis are also a major cause of hyperglycemia in type 2 diabetes and strictly impair insulin sensitivity." (PMID 39794453, 2025). "Confirmation of this novel physiological role for Cx36H in β-cells would place them as new susceptibility locus for type 1 and type 2 diabetes, whose physiological implication in the mechanism of insulin secretion regulation should be evaluated by in vivo studies in diabetic patients." (PMID 41227290, 2025). "In the area of metabolic health, vitamin K improves insulin sensitivity, modulates adipokines like adiponectin, and may lower the risk of metabolic syndrome and type 2 diabetes." (PMID 40718363, 2025). "Ameliorated insulin sensitivity, improved fat oxidation, and reduced cardiometabolic risk in individuals with type 2 diabetes were found after 6 weeks of a HIFT program including short 8–20 min high-intensity workouts at >85% HRmax, with a concomitant β-cell function improvement." (PMID 40247924, 2025). "Type 2 diabetes accounts for approximately 90% of cases, and the associated pathological mechanism involves the accumulation of fat in skeletal muscle and the liver, generating resistance to insulin action in these tissues." (PMID 41009376, 2025). "A higher number of CAG repeats is linked to lower AR transcriptional activity, which may negatively affect glucose homeostasis and insulin action, increasing the risk of type 2 diabetes." (PMID 41300761, 2025). "Notably, the accumulation of ectopic fat within and surrounding the pancreas, referred to as pancreatic steatosis, has been implicated in impaired insulin secretion, increased risk of type 2 diabetes, and heightened vulnerability to pancreatitis." (PMID 40693271, 2025). "Type 2 diabetes in children is caused by pancreatic beta-cell dysfunction combined with insulin resistance due to obesity, particularly the accumulation of visceral fat, which leads to insufficient insulin action." (PMID 41257150, 2025). "It scored high risk for patient selection as it excluded insulin‐treated type 2 diabetes patients." (PMID 39400428, 2025). "In these reports, while endogenous insulin secretion was preserved and the risk of insulin deficiency was low, it is recommended that treatment be carried out in accordance with the guidelines for type 2 diabetes, except for the use of sulfonylurea agents." (PMID 40226121, 2025). "GLP-1 RAs improve glycaemic control through glucose-dependent insulin secretion, glucagon suppression, slowed gastric emptying, and enhanced satiety, yielding HbA1c reductions, weight loss, and cardiovascular benefits in type 2 diabetes." (PMID 41226286, 2025). "Dysregulation of INS signalling—whether due to excess or deficiency—is a major initiating factor and/or contributor to metabolic disorders such as obesity, type 2 diabetes, dyslipidemia, atherosclerosis, and hypertension." (PMID 40940769, 2025). "It is deficient in type 1 diabetes and relatively higher in insulin-requiring type 2 diabetes." (PMID 39851552, 2025). "For example, ketogenic diets should be used with caution or avoided in individuals with type 1 diabetes, advanced type 2 diabetes treated with insulin or SGLT2 inhibitors (due to risk of ketoacidosis), disorders of fatty acid oxidation, or hepatic and renal insufficiency." (PMID 41228543, 2025).
type 2 diabetes (continued). "Notably, Tcf7l2 has been strongly associated with type 2 diabetes and is involved in glucose homeostasis and insulin secretion in pancreatic β cells." (PMID 40971438, 2025). "While there is ongoing debate between epidemiological findings and neuropathological observations regarding the relationship between type 2 diabetes and AD, experimental research has linked insulin and insulin resistance to the pathogenesis of AD in several ways." (PMID 40149843, 2025). "Chronic overnutrition, particularly sustained fatty acid (FA) overload, is a major risk factor for type 2 diabetes, as it dysregulates the mechanistic target of rapamycin complex 1 (mTORC1) signaling, leading to impaired β-cell insulin secretion and reduced insulin sensitivity." (PMID 40076537, 2025). "The association between thyroid function and type 2 diabetes has long been hypothesized due to the effects of thyroid hormones on carbohydrate and lipid metabolism, as well as insulin secretion." (PMID 40150555, 2025). "The condition is broadly classified into type 1 diabetes, which is caused by autoimmune destruction of pancreatic β-cells leading to absolute insulin deficiency, and type 2 diabetes, which involves insulin resistance combined with a relative insulin secretory defect." (PMID 40710154, 2025). "In this study, CBT therapy reduced depressive symptoms, but this improvement in mental health did not translate into an overall reduction in BMI in all patients; however, an improvement in fasting insulin levels, an important marker of risk for type 2 diabetes, was observed." (PMID 41300629, 2025). "Tirzepatide is a dual glucagon-like peptide-1 (GLP-1) and glucose-dependent insulinotropic polypeptide (GIP) receptor agonist that enhances glucose-dependent insulin secretion, suppresses glucagon, and slows gastric emptying, making it highly effective for weight loss and type 2 diabetes management." (PMID 41368024, 2025). "Our results show that xylitol consumption prior to meals leads to a lower energy intake and modulates postprandial insulin and glucose concentrations, highlighting its potential to support glycemic control and appetite regulation in individuals at risk for or living with type 2 diabetes." (PMID 39940340, 2025). "For example, recent genome-wide association studies identified multiple genetic variants associated with type 2 diabetes that may affect insulin secretion and islet β-cell function." (PMID 39881429, 2025). "According to Bowker and associates in 2006, patients experiencing type 2 diabetes who were subjected to exogenous insulin and sulfonylureas were at considerably higher risk of dying from cancer than those who were administered metformin [RR 0.82; 95% CI (0.61–0.91)]." (PMID 40572709, 2025). "The underlying etiology and pathophysiology classify diabetes into type 1 diabetes, an autoimmune disease characterized by beta-cell destruction, and type 2 diabetes, which is caused by the inability of cells to respond properly to the actions of insulin due to insulin resistance." (PMID 41573197, 2025). "The ArfGAP with RhoGAP domain, ankyrin repeat, and PH domain-containing protein 1 (ARAP1) rs1552224 locus has been identified as a risk locus for type 2 diabetes, and recent reports have linked it to elevated blood glucose levels and reduced insulin release upon glucose stimulation." (PMID 41036138, 2025). "A study involving clinical patient samples and a type 2 diabetes rat model demonstrated a significant positive correlation between cognitive function and serum OC levels, with reduced OC levels in diabetic patients linked to insulin dysfunction." (PMID 40417692, 2025). "Regular PA may also help regulate blood sugar levels and improve insulin sensitivity, reducing the risk of type 2 diabetes and metabolic syndrome." (PMID 40177092, 2025). "Excessive selenium may lead to oxidative stress, harming pancreatic β-cells and insulin-sensitive tissues, eventually increasing the risk of type 2 diabetes." (PMID 39149550, 2024).
type 2 diabetes (continued). "Regular exercise, including aerobic and resistance training, has been consistently associated with higher adiponectin levels, increased insulin sensitivity, and reduced systemic inflammation in various populations, including those with metabolic syndrome and type 2 diabetes." (PMID 39125318, 2024). "Our results suggest that the inverse association of EGP with LDL-C might indicate that LDL-C decreases EGP, thus improving hepatic insulin sensitivity and paradoxically reducing the risk of type 2 diabetes in adults with MetS." (PMID 38989003, 2024). "Furthermore, it’s noteworthy that the DII has been identified as being associated with all indicators of type 2 diabetes risk, including fasting glucose, insulin levels, and HbA1c, with obesity serving as a mediating factor." (PMID 38291352, 2024). "However, in type-2 diabetes, a reduction in insulin secretion and a reduced sensitivity to insulin cause an excess of blood glucose leading to chronic hyperglycemia." (PMID 38565895, 2024). "Oxidative stress-induced type 2 diabetes primarily affects the insulin signaling pathway, particularly through lipid oxidative damage to the cell membrane where the insulin receptor resides, reducing insulin function and causing insulin resistance." (PMID 38671942, 2024). "However, the use of GLP1-ra was associated with an increased risk of diabetic retinopathy in individuals with type 2 diabetes also taking insulin." (PMID 38584180, 2024). "Recent studies have found that the GlyNAC complex can correct GSH deficiency, counteract oxidative stress, correct type II diabetes, reduce insulin resistance, enhance muscle strength, and improve cognitive function in older adults, suggesting that it has anti-aging effects." (PMID 37975960, 2024). "Therefore, the deficiency of insulin caused by impaired quality and quantity of β‐cells is associated with the pathogenesis of type 2 diabetes mellitus (T2DM)." (PMID 38884322, 2024). "Since added sugars in beverages raise blood glucose and insulin levels, which may lead to an increased risk of type 2 diabetes." (PMID 39845658, 2024). "Previous large prospective studies have shown that high dietary fiber intake, especially insoluble cereal dietary fiber is associated with a reduced risk of type 2 diabetes by potentially improving insulin sensitivity, inflammatory markers, and intestinal microbiota." (PMID 38989003, 2024). "This cohort study evaluates whether glucagon-like peptide receptor agonists (GLP-1RAs) are associated with risk of obesity-associated cancer among patients with type 2 diabetes compared with insulin or metformin." (PMID 38967919, 2024). "Japanese men with type 2 diabetes who actively engage in leisure-time physical activity tend to experience improved glycemic control, reduced cardiovascular risk factors, a decreased need for insulin, and potential mitigation of retinal aging." (PMID 39268236, 2024). "The combined deficit of vitamin D and magnesium may lead to clinically relevant outcomes, including not only a higher risk of fragility fractures but also altered insulin secretion and action contributing to an increased risk of incident type 2 diabetes." (PMID 38892495, 2024). "The decrease in insulin secretion due to the incomplete function of β-cells or the resistance of peripheral tissues (liver tissue, fat, and skeletal muscles) to insulin, is characteristic of type 2 diabetes which causes hyperglycemia disorder." (PMID 38565703, 2024). "A recent randomized clinical trial found that sumatriptan reduced insulin sensitivity and glucose effectiveness in overweight humans, and a cohort study found that valproate was associated with a higher risk of developing type 2 diabetes in adults." (PMID 39333866, 2024). "Of note, we observed that BMI, fasting insulin, and type 2 diabetes seemed to partly mediate the associations of LST and MVPA with gastrointestinal diseases, which indicates that metabolic factors may be involved in the pathological process." (PMID 38583262, 2024).